INS (insulin)
Diseases named in the same sentence as INS in open-access papers (continued):
Sharing a sentence is not in itself a finding about the gene and the disease.
Insulin resistance (continued). "The impairment of insulin action on its receptor results in a condition of insulin resistance which is associated by an increase in beta cell insulin production and hyperinsulinemia." (PMID 34946711, 2021). "The HFCD initiated a metabolic cascade of elevated lipid profiles, hypertriglyceridemia, hyperglycemia, oxidative stress, insulin, and inflammatory biomarkers implicated in insulin resistance and NAFLD." (PMID 34037093, 2021). "Insulin resistance is defined as the loss of insulin effects on target tissues, observed in patients with type 2 diabetes mellitus." (PMID 33441784, 2021). "Data from people with obesity support the notion that hepatic GABA production and transport are associated with serum insulin, homeostatic model assessment for insulin resistance (HOMA-IR), T2D, and BMI." (PMID 34192532, 2021). "Deletion of β-catenin in skeletal muscle was found to diminish insulin-stimulated glucose transport in mice, and this was also associated with mild glucose intolerance and insulin resistance." (PMID 34568323, 2021). "Scenario C - High Insulin Resistance (Late Pregnancy Conditions): Due to the significantly low insulin sensitivity, subjects have a higher risk of hyperglycemia." (PMID 35392357, 2021). "Adipose tissue inflammation causes the disruption of the physiological response to insulin, leading to insulin resistance and, consequently, to systemic hyperglycaemia." (PMID 33578952, 2021). "The apparent cause of dyslipidemia—a feature of insulin resistance (IR) syndrome, characterized by elevated triglyceride and small dense low-density lipoprotein levels with low high-density lipoprotein levels—is insulin activity inhibition." (PMID 33401717, 2021). "Both mechanisms have been linked to elevated insulin levels associated with obesity-induced insulin resistance." (PMID 33596230, 2021). "Visceral fat accumulation is associated with insulin resistance, while subcutaneous fat plays a role in reducing insulin levels and improving insulin sensitivity." (PMID 33876723, 2021). "In fact, T2DM is mainly associated with insulin resistance (IR) and decreased insulin sensitivity due to impaired insulin signal transduction." (PMID 35111058, 2021). "The injection of exosomes collected from the adipose tissue macrophages of obese mice into lean mice caused glucose intolerance and insulin resistance, whereas the reverse improved insulin sensitivity in obese mice." (PMID 34831343, 2021). "At the level of tissues and cells, the basic pathophysiological mechanism underlying the disturbance of normal metabolic function is insulin resistance (IR)—an inability of tissues to respond to the insulin signal." (PMID 34205752, 2021). "We confirmed in this study that higher BMI is associated with increased insulin resistance and decreased insulin sensitivity in diagnosed type-2 DM." (PMID 34741064, 2021). "Obesity is intimately linked to insulin resistance, accompanied by elevated circulating insulin concentrations." (PMID 34211985, 2021). "Fetuin A null mice show improved insulin sensitivity, resistance to weight gain and are protected against obesity and insulin resistance associated with aging." (PMID 33499061, 2021). "In particular, sclerostin is associated with lower levels of insulin, alongside reduced insulin resistance in diabetic patients compared to controls." (PMID 33801212, 2021). "By contrast, other studies suggest increased plasma FFA are associated with compensatory insulin secretion responsible for maintaining almost unchanged glucose tolerance in the face of increasing insulin resistance." (PMID 33815283, 2021). "Insulin plays an important role in disorders of glucose and lipid metabolism (e.g. impaired glucose tolerance and insulin resistance) are associated with body weight loss induced by CAC." (PMID 34863141, 2021).
Insulin resistance (continued). "As increased levels of long-chain acylcarnitines have been linked to insulin resistance, we investigated the effects of long-chain acylcarnitines on key components of the insulin signalling pathway." (PMID 34208786, 2021). "Type 2 DM (T2DM) is characterized by impaired insulin secretion due to a gradual loss of β-cell function and a long-term over-production of insulin to compensate for insulin resistance." (PMID 34068827, 2021). "In men, insulin resistance impaired vascular nitric oxide production and insulin-induced vasodilation, both of which are likely to cause sexual dysfunction." (PMID 34421613, 2021). "Effective mitochondrial volume is vital for insulin signaling and glucose homeostasis, and any impairment in this pathway increases the risk of insulin resistance." (PMID 34660812, 2021). "Insulin resistance is defined as impaired response of cells and tissues to the insulin action, causing increased blood glucose." (PMID 34938272, 2021). "Homozygous carriers of the BclI polymorphism have been associated with increased body weight, Body Mass Index (BMI), abdominal obesity, fasting plasma glucose, insulin, index of insulin resistance (HOMA), and deficient GR function." (PMID 34681832, 2021). "In humans, plasma BAIBA levels were increased with exercise and inversely associated with metabolic risk factors, such as fasting glucose, insulin, homeostasis model assessment of insulin resistance (HOMA-IR), and the levels of TG and TC." (PMID 34206159, 2021). "The depletion of M1 macrophages normalizes sensitivity to insulin in obese mice, whereas the reduction of M2 macrophage numbers predisposes lean subjects to insulin resistance." (PMID 34043673, 2021). "High levels of insulin can cause insulin receptor degradation and drive early podocyte insulin resistance, and both the insulin receptor and nephrin are needed for full insulin sensitivity of podocytes." (PMID 33628839, 2021). "The direction of causality between insulin resistance and reduced insulin clearance has been debated." (PMID 34206745, 2021). "As alterations in the gut microbiome have been shown to regulate brain insulin sensitivity, it is possible that AD-associated changes in the microbiome result in insulin resistance within the brain." (PMID 33800340, 2021). "Insulin resistance, a state of inadequate response to insulin, is considered to be a hallmark of type 2 diabetes, and it is also observed in neurodegenerative disease." (PMID 34966358, 2021). "Glucose homeostasis is the balance between the insulin and the glucagon in the blood to preserve the blood glucose levels, and it is associated with peripheral insulin resistance." (PMID 34674647, 2021). "T2DM is caused by impaired insulin secretion, which generally occurs in the context of pre-existing insulin resistance." (PMID 34827690, 2021). "To further dissect the mechanism underlying miR29‐mediated systemic insulin resistance, we analysed miR‐29s levels and their effects on insulin action in the liver, skeletal muscle and gonadal adipose tissue of mice injected with exosomes." (PMID 33520119, 2021). "One of them, miR-122, which was increased, correlated positively with dyslipidemia, NAFLD and insulin resistance in children, while several genes targeted by miR-122 have been associated with insulin resistance and skeletal muscle response to insulin." (PMID 33800718, 2021). "Unfolded protein response (UPR) caused by ER dysfunction is known as ER stress, which is related to metabolic diseases including insulin resistance and obesity because induced ER stress prevents weight loss and anorexic functions of insulin and leptin." (PMID 33763034, 2021). "Anti-TNFα agents improve insulin sensitivity and decrease insulin resistance in RA patients, also reducing the risk of developing T2D." (PMID 33995414, 2021).
Insulin resistance (continued). "For example, high amount of lactate-producing Collinsella (Actinobacteria) is associated with increased circulating levels of insulin, homeostatic model assessment of insulin resistance (HOMA-IR), triglycerides, and very-low-density lipoproteins." (PMID 35128441, 2021). "One of the most widely proposed pathways in the progression of NAFLD and hepatic fibrosis is the metabolic or insulin signaling pathway, which is associated with insulin resistance/hyperinsulinemia and hyperglycemia." (PMID 34943908, 2021). "In a study on the American adult population, AA was found to be associated with reduced serum insulin levels and homeostasis model assessment of insulin resistance." (PMID 34831705, 2021). "GDM is characterized by insulin resistance caused by insufficient insulin production during later stages of pregnancy." (PMID 34828683, 2021). "In fact, activation of inflammatory pathways and impaired insulin mediated vasodilatation are associated to higher risk of T2D and contribute to muscle insulin resistance." (PMID 33320449, 2021). "Insulin resistance (IR) is the decreased sensitivity of tissues to insulin and is a predisposing factor for hyperglycaemia, higher blood pressure and dyslipidaemia." (PMID 33532603, 2021). "FFAs abolish insulin’s action in muscle and liver, and consequently induce hyperglycemia and insulin resistance which is considered to increase the T2D risk." (PMID 34740359, 2021). "Perturbation of organ crosstalk is a hallmark of insulin resistance, emphasizing the importance of crosstalk molecules in the modulation of insulin signaling, potentially leading to defects in insulin action." (PMID 34440850, 2021). "Human obesity is also frequently associated with resistance to both leptin and insulin, and genome-wide association studies have implicated mutations near the melanocortin receptor-4 in the development of obesity and insulin resistance." (PMID 34604220, 2021). "Dyslipidemia of insulin resistance is a key risk factor for cardiovascular disease, precedes the onset of dysglycemia, and reflects adipose tissue and hepatic responses to insulin signaling defects." (PMID 34084151, 2021). "Type 2 diabetes is a metabolic disorder that results in insulin resistance and hyperglycemia, and loss of function mutations in the insulin signaling mediators have been related with the onset of the disease." (PMID 34440853, 2021). "Subjects with adiponectin deficiency developed insulin resistance in the brain and impaired downstream insulin signaling, leading to AD pathology." (PMID 33849621, 2021). "On the other hand, the virulent strains of H. pylori (cag + with induction of inflammatory factors 71, IL6, CRP) and chronic inflammation affect the insulin-regulating gastroduodenal hormones and ultimately predispose the person to insulin resistance." (PMID 34922625, 2021). "Noteworthy, both insulin resistance and diabetes type 2 have been associated with reduced availability of D-Chiro-Ins, suggesting that it should act as insulin second messenger and insulin-sensitizing agent." (PMID 33889133, 2021). "In this regard, it is now clear that in women with PCOS, usually associated with insulin resistance, as well as with defects in insulin secretion, ovarian reserve is better preserved than in normo-ovulatory women of similar age." (PMID 35118400, 2021). "Liver damage is associated with hepatic insulin resistance, insulin secretion, oxidative stress, and inflammation in healthy adults." (PMID 34359426, 2021). "Early studies suggested that loss-of-function mutations in p110α impair insulin signaling causing insulin resistance and inducing a pre-diabetic state." (PMID 33431926, 2021). "Some PTPs, such as PTPN1, PTPN9, PTPN11, PTPRF, PTPRS, and dual specificity phosphatase 9 (DUSP-9), lead to type 2 diabetes associated insulin resistance through antagonism of insulin action." (PMID 33799458, 2021).
Insulin resistance (continued). "Damage to islet β‐cells affects the production and secretion of insulin, which in turn causes the body's internal substance and energy metabolism disorders and insulin resistance." (PMID 34026064, 2021). "Poor glycemic control is associated with high levels of glucose, insulin resistance, and high levels of fasting insulin." (PMID 33413444, 2021). "Accumulation of fatty acids and triglycerides alters mitochondrial function, causing an impaired capacity of insulin to suppress hepatic gluconeogenesis in fatty liver, leading in turn to the development of insulin resistance." (PMID 34676828, 2021). "Obesity can cause alterations in insulin sensitivity, and insulin-resistance in the heart has important implications for cardiac metabolism and function." (PMID 34769060, 2021). "Insulin resistance that attenuated biological response to insulin circulation was reported to be associated with a series of pathological conditions and some endocrine tumors, including breast cancer." (PMID 32802855, 2020). "His exhibited a protective effect on glucose, insulin, insulin resistance, lipid profile, cardiac risk ratios, renal functional markers, oxidative stress, and TNF-α." (PMID 32695286, 2020). "Some researchers have linked hyperglycemia to peripheral insulin resistance, reduced insulin secretion, or disorder in insulin metabolism." (PMID 32904566, 2020). "On the other hand, oxidative stress caused by hyperglycemia in diabetic patients can reduce insulin signaling, thus leading to insulin resistance." (PMID 32927712, 2020). "This study demonstrated that mouse Chr 11 harbors a gene or genes involved in high sucrose-induced development of type 2 diabetes associated with impaired insulin secretion, insulin resistance, obesity, and fatty liver." (PMID 32703163, 2020). "Skeletal muscle insulin resistance, an important feature of type 2 diabetes, is caused by a reduced ability of muscle to respond to circulating insulin and has been related with intracellular lipid accumulation." (PMID 33322719, 2020). "Numerous studies have demonstrated that the low level of Ca2+ in the cells of insulin targeted tissues is associated with reduced activity of glucose transporter followed by the development of peripheral insulin resistance." (PMID 32932777, 2020). "In a rodent model of insulin resistance caused by obesity, the genetic ablation of TNFα, or its receptor, improved insulin sensitivity." (PMID 32575419, 2020). "It has been postulated that as the skeletal muscle is a major target of insulin action, muscle wasting (sarcopenia) promotes insulin resistance with increased risk of hyperglycemia." (PMID 33339220, 2020). "Supporting a direct role of iron in metabolic disease risk, iron chelation improves insulin sensitivity in humans and in mice with insulin resistance." (PMID 33133674, 2020). "Of note, ineffective insulin/IGF-1 signaling resulting from insulin resistance is a risk factor for AD, where the presence of T2DM doubles the risk of AD16,61,76." (PMID 32226608, 2020). "Insulin resistance is a central component of metabolic syndrome and while high levels of daily physical activity can prevent insulin resistance, physical inactivity is a primary cause of insulin resistance and a loss of insulin sensitivity in skeletal muscle." (PMID 32466598, 2020). "PCOS is a widely studied syndrome associated with insulin resistance, for which insulin-sensitizing factors have been proposed as putative treatments to improve the hyperinsulinemia-related dysfunction of ovarian response to endogenous gonadotropins." (PMID 32646482, 2020). "As a negative feedback regulator of the insulin signal transduction pathway, TRB3 can affect the insulin signal transduction pathway by inhibiting the function of Akt, which then causes insulin resistance." (PMID 32774144, 2020).
Insulin resistance (continued). "The colocalization of IDE and SNX5 next to the BBM reduces insulin levels while deficiency of one or both regulators leads to increased circulating insulin levels decreasing IRec expression and inducing insulin resistance." (PMID 32377524, 2020). "Low levels of n-3 and high n-6 in phospholipids of cellular muscle cell membranes are associated with an increase in their resistance to insulin, which promotes the development of insulin resistance and type II diabetes." (PMID 32092918, 2020). "Type 2 diabetes (T2D), due to a progressive loss of adequate β-cell insulin secretion frequently on the background of insulin resistance, accounts for nearly 90% of cases." (PMID 32927754, 2020). "These include epidemiological studies, which found high fasting insulin levels (and concomitant insulin resistance) in children and adolescents to be associated with higher weight gain in later years." (PMID 32819363, 2020). "Neu3 sialidase activity induced by olanzapine, an antipsychotic agent associated with insulin resistance, attenuated insulin-induced phosphorylation of insulin growth factor receptor and IRS1, contributing to insulin resistance." (PMID 32251344, 2020). "It has been suggested that hypertrophy is associated with relative insulin sensitivity or early insulin resistance and hyperplasia with greater insulin resistance and T2D." (PMID 31941045, 2020). "Genome-wide association studies (GWAS) have identified common variants for quantitative traits (insulin resistance and impaired insulin release) of type 2 diabetes (T2D) across different ethnics including China, but results were inconsistent." (PMID 32260174, 2020). "Insulin secretion, as well as insulin resistance, can be evaluated to identify the potential risk of liver fibrosis progression." (PMID 33102766, 2020). "On one end, chronic exposure to insulin can lead to insulin resistance and dysfunctional insulin signaling which are associated with the suboptimal post-insult recovery and the development of certain proteinopathies." (PMID 33100956, 2020). "Our findings are reflective of the complex overlap of metabolic aberrations such as insulin resistance and weight-dependent, altered insulin metabolism associated with obesity and PCOS, which compound the risk of developing GDM." (PMID 32831037, 2020). "Insulin resistance impairs brain function, and a large body of evidence suggests a link between impaired insulin function and the risk of developing Alzheimer’s Disease (AD) and other neurodegenerative diseases." (PMID 33374894, 2020). "As previous studies have demonstrated that prediabetes was an impaired glucose regulation state which mainly caused by the pancreatic β cell dysfunction with insulin secretion and hepatic insulin resistance (IR) cell damage." (PMID 32881889, 2020). "Next, we evaluated the effects of L. paracasei HII01 on TG accumulation in both the skeletal muscle and liver because the accumulation of lipid within target tissues of insulin is closely associated with insulin resistance and abnormal lipid metabolism." (PMID 33019697, 2020). "It is well characterized that pS273 is linked to obesity and insulin resistance and blocking pSer273 by specific PPARγ ligands shows improved insulin sensitivity." (PMID 32024237, 2020). "In fact, clenbuterol fully abolished insulin resistance caused by high-fat diet, since clenbuterol-treated mice responded to insulin similarly to chow-fed mice, which were, however, tested at a separate occasion." (PMID 32472192, 2020). "Adiponectin has been associated with maintaining insulin sensitivity, and lowered adiponectin is associated with insulin resistance/type II diabetes and dyslipidemia as well as cardiovascular pathologies." (PMID 32403966, 2020).